Y_RNA (Y RNA )
Gene: Miscellaneous RNA gene on chromosome 3 (38,505,480 to 38,505,581, reverse strand). Ensembl gene ENSG00000207512.
Homologues: Orthologues: chimpanzee Y_RNA (100% identical), macaque Y_RNA (94% identical). Paralogues in human: Y_RNA (92% identical), Y_RNA (91% identical), RNY3 (90% identical), Y_RNA (90% identical), RNY3P1 (89% identical), Y_RNA (89% identical), Y_RNA (88% identical), RNY3P16 (87% identical), Y_RNA (87% identical), Y_RNA (86% identical), RNY3P14 (85% identical), Y_RNA (85% identical), and 98 more.